HMGB1 (high mobility group box 1)
Diseases named in the same sentence as HMGB1 in open-access papers (continued):
Sharing a sentence is not in itself a finding about the gene and the disease.
melanoma (continued). "We also observed that HMGB1 directly induced the production of IL-10 in TAMs and that blockade of IL-10 with a neutralizing antibody led to delayed tumour growth in the B16 mouse melanoma model." (PMID 27426915, 2016). "Indeed, UVB radiation of the skin has been shown to induce HMGB1 release from epidermal keratinocytes, resulting in a neutrophilic inflammatory response that stimulate angiogenesis and promotes melanoma metastasis in mice." (PMID 27426915, 2016). "Additionally, increased HMGB1 levels were measured in the sera of melanoma patients treated with IL RB." (PMID 27177220, 2016). "The intracellular amount of HMGB1 is significantly increased in several human tumors such as lung, bladder, colorectal, head and neck, prostate, hepatocellular, and gastric cancer and melanoma." (PMID 27294158, 2016). "To assess whether HMGB1 plays a functional role in melanoma progression, we diminished HMGB1 expression in B16 melanoma cells using shRNA technology." (PMID 27426915, 2016). "Here we show that the damage-associated molecular pattern High-Mobility Group Box 1 protein (HMGB1) is released by melanoma tumour cells as a consequence of hypoxia and promotes M2-like tumour-associated macrophage accumulation and an IL-10 rich milieu within the tumour." (PMID 27426915, 2016). "In exogenous Hmgb1 treated cells, significant increas in p-NF-κB level, but decrease in Klotho protein expression, was observed in A375 and SK-28 melanoma cells." (PMID 27779100, 2016). "Tumour-derived HMGB1 released as a consequence of focal intra-tumoural hypoxia thus directly contributes to tumour progression and likely represents an attractive therapeutic target for tumour therapy as demonstrated here in the case of melanoma." (PMID 27426915, 2016). "To determine whether HMGB1 release in this mouse model of melanoma was reminiscent of what was observed in human melanoma metastases, we assessed the intra-cellular localization of HMGB1 in tumours of mice implanted s.c. with lamin-shRNA-transduced B16 cells." (PMID 27426915, 2016). "Moreover, the increase of HMGB1 expression correlated with the progression of melanoma and with poorer melanoma patient survival." (PMID 25051367, 2014). "Thus, the Hmgb1-IL-23-IL-17-IL-6-Stat3 axis contributes to tumor development in murine models of melanoma." (PMID 24453427, 2013). "All these data suggest that Hmgb1-IL-23-IL-17-IL-6-Stat3 axis plays a pivotal role in tumor development in murine models of melanoma, and blocking any portion of this axis will attenuate melanoma tumor growth." (PMID 24453427, 2013). "Moreover, the GSDME protein levels in cancer cells are not as invariable as those in normal cells, and BRAF/MEK inhibitors can promote the cleavage of GSDME and the release of high-mobility group box 1 (HMGB1), which are markers of pyroptotic cell death in melanoma cells." (PMID 38336727, 2024). "Moreover, pyroptosis can release HMGB1 and enhance the progression of melanoma." (PMID 35896522, 2022). "Further evidence that the production of HMGB1/RAGE-dependent IL-10 by macrophages promotes melanoma growth has come from a human melanoma tissue study, in which high infiltration of IL-10-producing macrophages was detected in melanoma tissue with a high expression of HMGB1." (PMID 36012593, 2022). "Knockdown of HMGB1 could enhance melanoma cell death that is induced by ALO treatment." (PMID 32536835, 2020). "In addition, the correlation of HMGB1 and melanoma has been reported." (PMID 32536835, 2020). "Here, we demonstrate that 8-MOP plus UVA light reduces melanoma cell viability along with the emission of ICD-associated danger signals including calreticulin (CALR) exposure on the cell surface and secretion of ATP, high mobility group box 1 (HMGB1) and type I interferon (IFN)." (PMID 31371700, 2019).
melanoma (continued). "In further support for a potential role of TAMs and IL-10 in melanoma is the presence of IL-10-producing TAMs in human melanoma metastases as revealed by the presence of CD163+ IL-10+ cells infiltrating human metastases in areas with high cytoplasmic HMGB1 expression." (PMID 27426915, 2016). "Consistent with a nuclear function of HMGB1, we demonstrated that HMGB1 regulated cell proliferation via interacting with Sp1 and interfering Sp1-mediated transcription of p21 Together, our study reveals a novel oncogenic role of HMGB1 in promoting human melanoma cell proliferation." (PMID 25051367, 2014). "In line with such an association, a number of clinicopathological characteristics of higher-grade melanoma including the tumor thickness, mitotic index, lymph node metastasis, and distance metastasis also exhibited a positive correlation with a higher level of HMGB1." (PMID 25051367, 2014). "T-VEC, belonging to herpes simplex virus type 1 (HSV-1), has been found to induce the release of high mobility group box 1 (HMGB1) protein and calmodulin in human melanoma cells." (PMID 40539780, 2025). "In melanoma, increased expression of the TLR4 agonist HMGB1 enhances the proliferation of tumor cells, but its correlation with patient survival and melanoma progression is low." (PMID 40969278, 2025). "Glycyrrhizin improves lung metastasis in melanoma, and further experiments show that it weakens NF-KB and ERK1/2 expression by acting on the HMGB1/RAGE axis, inhibiting melanoma lung metastasis." (PMID 38529373, 2024). "This was accompanied by a reduction of HMGB1 and HMGN1 in melanoma cell lysates, indicating that LTX-315 treatment results in the translocation/release of both these DAMPs/alarmins from A375 and B16F10 cells into the supernatant." (PMID 38545099, 2024). "Recent studies suggest that HMGB1 and RAGE are also involved in the development of basal cell carcinoma and melanoma, although their roles differ across these skin cancer types." (PMID 39769332, 2024). "This BRAFi-mediated tumor cell death was linked to the release of the inflammatory molecules High-Mobility-Group-Protein B1 (HMGB1) and Heat Shock Protein 90 (HSP90) from D4M melanoma cells." (PMID 38631706, 2024). "On RAGE independent pathways, HMGB1 interacts with erythropoietin-producing human hepatocellular B4 (EPHB4), NF-κB, TLR4 and melanoma inhibitory activity (MIA) protein to induce its tumorigenic effects and affect autophagy." (PMID 37511951, 2023). "Photodynamic therapy of B16 melanoma leads to enhanced ecto-CRT and an increased release of DAMPs, including HMGB1 and IFN1." (PMID 37626741, 2023). "In an in vivo melanoma model, ultraviolet (UV) irradiation induced a TLR4/MYD88-driven neutrophilic skin inflammatory response initiated by high mobility group box 1 (HMGB1) release from ultraviolet-damaged keratinocytes." (PMID 37525065, 2023). "proved that extracellular HMGB1 is an essential factor for TLR4 interaction with platelets and promotes melanoma tumor cells’ interaction with aggregation, extravasation, and metastasis." (PMID 37168380, 2023). "In the hypoxic TME of melanoma, tumor cells accumulate HIF-1 and also release high mobility group box 1(HMGB-1), which induces macrophages to produce IL-10 driving them to an M2-like phenotype that promotes proliferation and metastasis." (PMID 36816959, 2023). "NDV/FMV strain-infected melanoma, lung cancer, and prostate cancer cells also displayed HSP70/90 and ATP secretion in addition to CRT exposure and HMGB1 release." (PMID 36755812, 2022). "It has been reported that this product inhibits pulmonary metastasis in mice inoculated with B16 melanoma (a murine tumor cell line used for research as a model for human skin cancers) by regulating the HMGB1/RAGE and HMGB1/TLR4 signal transduction pathways." (PMID 36012593, 2022).
melanoma (continued). "In other studies, hyperthermia (41.5°C, 1 hour) administered alone or in combination with radiation (2 Gy) was demonstrated to trigger the release of both proteins HSP70 and HMGB1 by dead and dying B16F10 melanoma cells." (PMID 34485114, 2021). "Here, we measured HMGB1 secretion by Western blotting and ELISA analysis of culture supernatants from PBS- or Salmonella-treated melanoma cells." (PMID 34207850, 2021). "Specifically, the addition of anti-HMGB1 significantly reduced the expression of iNOS and IL-1β secretion in WEHI-3 and RAW 264.7 cells co-cultured with Salmonella pre-treated melanoma cells." (PMID 34207850, 2021). "Recently, our research group found that ICRP induced the release of several DAMPs (CRT, ATP, HSP70, HSP90 and HMGB1), and ICD in B16F10 murine melanoma cells." (PMID 32660440, 2020). "For instance, although mafosfamide treatment induces HMGB1 release from both EG7 lymphoma cells and B16-F10 melanoma, this cyclophosphamide derivative promotes vaccine-verified ICD only in EG7 lymphoma." (PMID 29209327, 2017). "In the present study, B16F1 melanoma cells treated with LTX-401 in vitro were screened for the release of ATP and HMGB1 using a luciferase assay and Western blot analysis, respectively." (PMID 26881822, 2016). "Several IL6-associated cytokines have growth factor activity, and inflammatory mediators such as HMGB1, IL23, and IL17 can promote tumor growth by activating the IL6-STAT3 pathway in a mouse model of melanoma." (PMID 27163161, 2016). "We conclude that HMGB1, nucleotides and CD8+ T cells mediate zVAD-fmk induced anti-melanoma immune reactions in multimodal therapy settings." (PMID 25973681, 2015). "To clarify the mode of BRAFV600E melanoma cell death induced by the combination of SAHA and PLX4720, we monitored release of the intracellular protein high-mobility group protein B1 (HMGB1) in relation to activation of the caspase cascade." (PMID 23744355, 2013). "This indicates that Hmgb1-RAGE pathway contributed to secretion of IL-17 dependent on IL-23 production and then promotes melanoma tumor growth." (PMID 24453427, 2013). "Next, by TCGA analysis, the expression of MLLT3 was not significantly correlated with HMGB1 in melanoma." (PMID 39716999, 2025). "To further confirm that the ROCK2 (kinase)-HMGB1 TF-PDGFRA TG cascade promotes tumor metastasis, we constructed an independent validation cohort including 20 melanoma patients and collected matched primary and metastatic melanoma tumor samples for proteomic and phosphoproteomic analysis." (PMID 39039072, 2024). "HMGB proteins (specifically HMGB1) are involved in the response to immunogenic cell death occurring after RT, and HMGB2 is a known regulator of CD8+ T cells, required for anti-melanoma response." (PMID 38672598, 2024). "Furthermore, HMGB1 and S100A9 have been identified as key RAGE and TLR4 ligands within the melanoma microenvironment." (PMID 39769332, 2024). "The discovery of an autonomous cell response to UV damage by the HMGB1/RAGE pathway in melanocytes may contribute to their resistance to apoptosis and cell death, and may have implications for the early stages of melanoma formation." (PMID 38725632, 2024). "It upregulates DAMPs (HMGB1, HSPA4, and HSP90AA1) in melanoma cells, for example." (PMID 39759512, 2024). "T-VEC was shown to induce apoptosis in melanoma cells and trigger ICD hallmarks including ecto-CRT, HMGB1, and ATP release, resulting in the recruitment of tumor-specific CD8+ T cells and induction of proinflammatory responses in both injected and non-injected tumor sites." (PMID 36755812, 2022). "Targeting the UVB-induced HMGB1/RAGE axis could inhibit PD-L1 induction in UVB-exposed melanocytes and melanoma cells, which may serve as potential drug targets to mitigate immune escape of malignant and premalignant melanocytes." (PMID 36012593, 2022).
melanoma (continued). "CRT exposure, the release of HMGB1 and HSP70, HSP90, and the secretion of ATP in melanoma cells were detected, thus suggesting that oncolytic NDV/FMW might be a potent inducer of ICD in melanoma cells, which cooperates with several other forms of cell death." (PMID 36012593, 2022). "Moreover, we have also reported that the HS conditioning of melanoma cells belonging to the lysate increased Calreticulin (CRT) plasma membrane translocation and induced the release of HMGB1." (PMID 35805888, 2022). "Indeed, since inflammatory cytokines such I-IFNs and HMGB1 are released and stimulate DCs through MV-infected tumor cells, ICD occurs in human melanoma cells and enhances anti-tumor immune responses." (PMID 35488303, 2022). "In this study, we demonstrated that neutron irradiation of BPA-pretreated human melanoma A375 and oral squamous carcinoma SAS cells at a therapeutic dose induces an early induction of a high level of extracellular HMGB1 release, compared with the equivalent dose of γ-irradiation." (PMID 35336794, 2022). "This study aimed to investigate the function of absent in melanoma 2 inflammasome in murine allergic rhinitis and the interaction between high mobility group box 1 and the absent in melanoma 2 inflammasome." (PMID 33707120, 2022). "HMGB1 is significantly increased in metastatic melanoma in patients, and drives the accumulation of M2-macrophages with elevated expression of YM1, FIZZ1, IL-10 in murine model of melanoma." (PMID 32486098, 2020). "Also, UV-induced neutrophilic inflammatory response, including the release of high mobility group box 1 (HMGB1) and Toll-like receptor 4 (TLR4), promoted angiogenesis and metastasis in melanoma cells." (PMID 32630437, 2020). "Importantly, silencing RAGE in these melanocytes resulted in a decreased secretion of HMGB1 as well as decreased resistance to apoptosis, strongly suggesting that the HMGB1/RAGE axis contributes to the early stages of melanoma development." (PMID 33256110, 2020). "P2Et-driven activation of PERK in melanoma cells was found to promote ER-calcium release, disrupt mitochondrial membrane potential, and trigger upregulation of ICD drivers, surface calreticulin expression, and extracellular release of ATP and HMGB1." (PMID 31531232, 2019). "To test this hypothesis, we measured the ICD markers ATP, HMGB1, and HSP70/90 in supernatants after viral infection and checked the cell surface of infected melanoma cells for CRT expression (ecto-CRT)." (PMID 31192135, 2019). "In contrast, our results showed that PV-10 treatment induced necrosis in melanoma cells and the secretion of HMGB1, but not HSP70, while the amount of HSP90 was unchanged." (PMID 27177220, 2016). "The A375 and SK-28 melanoma cells were treated with exogenous Hmgb1 at 0.01 μg/ml, 0.05 μg/ml, 0.1 μg/ml, and 0.5 μg/ml of Hmgb1 protein with or without 100 μM of NF-κB inhibitor CAPE for 24 and 48 hrs." (PMID 27779100, 2016). "DMOG exposure of siRNA-transfected melanoma cells did not result in significant increase of HMGB1 release, therefore reinforcing the role of the hypoxia/HIF1α axis in HMGB1 secretion." (PMID 27426915, 2016). "Moreover, HMGB1 has been found to regulate cell proliferation and metastasis via RAGE and melanoma inhibitory activity (MIA) pathway in oral cancer." (PMID 25330185, 2014). "We analyzed nearly 100 cases of human melanoma and found that HMGB1 was highly overexpressed in melanoma samples relative to normal skin and nevi tissues." (PMID 25051367, 2014). "Additionally, glycyrrhizin could modulate the HMGB1/RAGE and HMGB1/TLR4 signaling pathways in melanoma, disrupting tumor metastasis, and growth." (PMID 37897664, 2024).
melanoma (continued). "Besides, in melanoma, the combination of BRAF and MEK inhibitors could promote the pyroptosis protein GSDME cleavage and HMGB1 release." (PMID 36032140, 2022). "Moreover, previous to the lysate generation, the melanoma cell lines were conditioned with a 42°C heat shock protocol, in order to induce DAMPs such as the plasma membrane translocation of calreticulin (CRT) and the release of HMGB1 protein." (PMID 31886313, 2019). "To assess whether HMGB1 release under hypoxic culture condition was dependent on HIF1α or not, we knocked HIF1α down using siRNA in two human melanoma cell lines." (PMID 27426915, 2016). "Developing HMGB1 as a vaccine for PCa is a feasible immunotherapeutic strategy as the previous study strongly support that peptides derived from HMGB1 engrafted in liposomes induced potent antigen-specific and tumor specific immunity against B16-OVA melanoma model." (PMID 23766911, 2013). "Moreover, we have also demonstrated that the HS treatment of melanoma cells before their final lysis for TRIMEL generation increases calreticulin (CALR) plasma membrane translocation and induces the release of high mobility group box 1 (HMGB1) protein and two well-described DAMPs." (PMID 29744371, 2018). "However, the nuclear protein HMGB1 did not change its abundance upon HS (p value = 0.5610; logFC = −0.14), indicating that this stimulus is only able to induce its secretion but not its expression by melanoma cells." (PMID 29744371, 2018). "Extracellular HMGB1 release was significantly increased in human squamous carcinoma SAS and melanoma A375 cells 24 h after neutron irradiation but not after γ-irradiation." (PMID 35336794, 2022). "In melanoma patients, the decreased number of eosinophils and the increased number of M-MDSCs as well as the increased baseline serum levels of the related inflammatory factors S100A8/A9 and HMGB1 indicate a lack of response to ipilimumab treatment." (PMID 32551121, 2020). "In addition, two different melanoma cell lines exhibited a similar response to reduced HMBG1 expression, indicating that the role of HMGB1 in melanoma cell proliferation is not cell line-dependent." (PMID 25051367, 2014). "Additionally, four other PRR families including C-type lectin receptors, retinoid acid-inducible gene 1 (RIG-1), absent in melanoma-2 (AIM-2), and receptor for advanced glycation end products (RAGE, also a receptor for high-mobility group box 1 (HMGB1)) have also been characterized." (PMID 29065888, 2017).